BRCA1 (BRCA1 DNA repair associated)
Diseases named in the same sentence as BRCA1 in open-access papers (continued):
Sharing a sentence is not in itself a finding about the gene and the disease.
breast cancer (continued). "Again, a key role played by VEGFA and angiopoieitn 2 in the neovascularization of BRCA1/2 related breast cancers has been highlighted." (PMID 25333258, 2015). "The oncogenic action of miR-20b in breast cancer models has been suggested to involve suppression of phosphatase and tensin homolog (PTEN) and BRCA1 (breast cancer 1, early onset)." (PMID 25893380, 2015). "Of the 22 patients with BRCA1 c.5263_5264insC, 9 were diagnosed with early onset breast cancer, 11 with TNBCs, 4 with bilateral breast cancer, and 6 with both breast and ovarian cancer." (PMID 26183948, 2015). "The results show that mutations in PALB2 are rare, but along with BRCA1 and BRCA2 are key breast cancer susceptibility genes in the Xinjiang region of China." (PMID 26489409, 2015). "BRCA1 inhibits IGF-I action, so BRCA1 deficiency also leads to increased expression of several IGF-I signaling pathway components in multiple experimental systems, including mice, mammary tumors, and cultured human cells." (PMID 26258011, 2015). "The ability of BRCA1 to mediate mammary tumor differentiation has been attributed to its inhibition of Slug (Snai2) and Twist expression, key mediators of EMT." (PMID 25970777, 2015). "Compared to sporadic breast cancers, both BRCA1- and BRCA2-related breast cancers are more likely to be high grade and poorly differentiated." (PMID 26496879, 2015). "Next to a small set of classical disease-defining genes such as BRCA-1/2, the estrogen receptor or HER2/neu, the canonical PI3K/AKT/mTOR signaling pathway forms another mutational hotspot in breast cancer." (PMID 26498353, 2015). "The results indicate that the expression of BRCA1 in breast cancer was aberrantly decreased at the transcriptional level." (PMID 25789047, 2015). "The role of S100A2 as a tumor suppressor is supported by study of BRCA1 mutant and basal-like breast cancer cell lines, in which S100A2 exogenous expression resulted in growth inhibition, while siRNA knockdown enhanced proliferation." (PMID 26097874, 2015). "This study aimed to evaluate the contribution of germline BRCA1, BRCA2 and PALB2 mutations and the CHEK2 c.1100delC allele to breast cancer in a high-risk South African cohort." (PMID 26577449, 2015). "Our data correlate with previous studies showing better response to cisplatin treatment in breast cancer patients with low BRCA1 levels, and studies showing increased BRCA1 expression in breast cancer cells after treatment with 1, 25D or vitamin D analogues." (PMID 25992773, 2015). "Aside from hereditary breast cancer, low BRCA1 expression occurs in sporadic breast cancers by means of promoter methylation or overexpression of transcriptional repressors." (PMID 25970777, 2015). "By doing so, we identified a set of miRNAs putatively involved in BRCA1 gene expression regulation and breast cancer development." (PMID 26392359, 2015). "Our prior cell culture and rodent model investigations of breast cancer provided evidence that the BRCA-1 gene was a molecular target for the AhR and various chromatin remodeling factors." (PMID 26715507, 2015). "In vitro work in MCF7 breast cancer cells demonstrated that BRCA1 knockdown induces the expression of IGF-1 mRNA in an estrogen receptor α-dependent manner, which was shown to correspond with increased IGF-1R activation and signaling." (PMID 26217584, 2015). "In 5%–10% patients, inherited mutations in highly penetrant cancer susceptibility genes, such as BRCA1 and BRCA2, are known to confer a significantly elevated risk (>10-fold) of breast cancer and their carrier relatives." (PMID 27600231, 2015). "A cohort of BRCA1 and BRCA2 mutation carriers >18 years old who underwent surgery for breast cancer at an academic hospital (1992–2011) and had pathology available for review were included for study." (PMID 26496879, 2015).
breast cancer (continued). "We evaluated Brca-1 CpG promoter methylation and expression in mammary tumors induced in Sprague–Dawley rats with the AhR agonist and mammary carcinogen 7,12-dimethyl-benzo(a)anthracene (DMBA)." (PMID 26715507, 2015). "The present study evaluated the relationships between Pit-1 and BRCA1 in breast cancer, and the effect of the administration of cisplatin and 3-Epi in breast cancer cell lines, primary cultures of human breast tumors, and mice models." (PMID 25992773, 2015). "We observed the same phenomenon by AZD2281 in BRCA wild-type breast cancer cell line MDA-MB-231 with BRCA1 or BRCA2 downregulation." (PMID 25975349, 2015). "A previous article reported the development of breast cancer in a 21-year-old woman with NF1 and BRCA1 mutations." (PMID 26604930, 2015). "Even though BRCA1 breast carcinomas harbor in the majority of the cases a TN phenotype (85% of the cases), luminal (ER-positive) or HER2-positive phenotypes also have been reported." (PMID 26426992, 2015). "The link between OV and breast cancer (BC) is well documented, however most of the studies have focused on hereditary BC/OV which can be attributed to BRCA1/2." (PMID 25779658, 2015). "miRNA profiles of 17 BRCA1- and 9 BRCA2-associated breast carcinomas were analyzed using microarrays." (PMID 26378051, 2015). "We and others have shown specific somatic profiles of CNAs characteristic for both BRCA1 and BRCA2-associated breast carcinomas." (PMID 26553136, 2015). "qRT-PCR analysis of miR-99a confirmed the microarray results showing that it was down-regulated in both BRCA1- and BRCA2-associated breast carcinomas compared to their normal breast tissue counterparts." (PMID 26378051, 2015). "In this study we have performed high-resolution copy number, LOH and gene expression profiling of 120 familial breast carcinomas selected from a larger cohort of 155 familial breast tumors, including BRCA1, BRCA2 and CHEK2 mutant tumors." (PMID 26553136, 2015). "We performed high-resolution SNP array and gene expression profiling of 120 familial breast carcinomas selected from a larger cohort of 155 familial breast tumors, including BRCA1, BRCA2, and CHEK2 mutant tumors." (PMID 26553136, 2015). "In 80% of BRCA1 breast carcinoma the protein expression is lost because of the deletion of the second allele." (PMID 25880076, 2015). "Patients with tumors with similar aCGH patterns as BRCA1- and/or BRCA2-mutated breast cancers were defined as having a BRCA-likeCGH status, others as non-BCRA-likeCGH." (PMID 24887359, 2014). "Deletion of BRCA1 exons 1-13 was detected in a 49-year-old woman in whom bilateral breast cancer was diagnosed at 35 and 40 years of age." (PMID 24686251, 2014). "Of the three distinct classes of “simple”, “amplifier” and “complex” DNA copy-number alterations defined for breast cancer, BRCA1+ breast cancer fits within the “complex” class." (PMID 24884718, 2014). "Hazard ratios for prostate cancer in the IMPACT study, (Cox regression analyses) and for breast cancer in the RMH study, (weighted retrospective Cox regression analyses), by BRCA1/2 mutation status." (PMID 24489760, 2014). "LOH of at least one locus on 9q was observed in 56% of transitional cell carcinomas (TCCs) in bladder cancer, and LOH of at least one locus at 17q21 (BRCA1 locus) was found in 60.53% of breast cancers." (PMID 24581183, 2014). "A duplication of BRCA1 exons 1-2 was identified in a 66-year-old woman in whom breast cancer was diagnosed at age 64 years." (PMID 24686251, 2014). "The BRCA1 and BRCA2 mutations together account for about 20–25% of hereditary breast cancers and about 5–10% of all breast cancers." (PMID 25374621, 2014).
breast cancer (continued). "A strong family history of breast cancer and/or carrying a germline mutation in the BRCA1 or BRCA2 gene, substantially increases breast cancer risk." (PMID 26034659, 2014). "Numerous studies have investigated the rate of BRCA1/2 mutations in triple-negative breast cancer (TNBC), with reported mutation rates ranging from 10 to 40% in this breast cancer subtype." (PMID 25475740, 2014). "Overexpression of miR-342 in these cells reduced ID4 and increased BRCA1 expression, supporting a possible role of this mechanism in breast cancer." (PMID 24475217, 2014). "For BRCA1 carriers, there were significant differences (Phet <0.01) in the HR for high grade (grade 3) and grades 1 and 2 breast cancer for SNPs at 10q26.12 (FGFR2) and at 12q24.21." (PMID 25919761, 2014). "Here we report for the first time that BRCA1 is critical for vitamin D3-mediated growth inhibition of breast cancer cells via co-regulation of cell cycle progression and p21waf1 expression." (PMID 25460500, 2014). "The derepression of transcriptional repression of these genes by removing the ZBRK1/CtIP/BRCA1 repressor complex has been reported to enhance mammary tumor growth or tumorigenesis." (PMID 24704793, 2014). "In present work, we demonstrated that miR-638 directly regulates BRCA1 expression in breast cancer, implying a critical role of miR-638 in the course of breast carcinogenesis and biological behaviors." (PMID 25228385, 2014). "For breast cancer, methylation has been noted in genes including BRCA1, p16, E-cadherin, H-cadherin, ATM, CST6, cyclin D2, PTEN, RASSF1A, APC, RARb2, GSTP1, ER, PR, as well as numerous other genes related to multiple pathways relevant for carcinogenesis." (PMID 24368439, 2014). "Mutations at or deregulation of certain genes (BRCA1, BRCA2, HER2, PIK3CA) and others play important roles in breast cancer." (PMID 25051360, 2014). "Approximately half of all hereditary breast cancers are due to a mutation in either BRCA1 or BRCA2, and approximately 80% of individuals with a mutation in either of these genes develop breast cancer by the age of 70 years." (PMID 24950059, 2014). "In this study, we used triple-negative MDA-MB-231, BRCA1-mutated HCC1937 and sporadic BRCA1-competent MCF-7 cell lines as models of breast cancer cell growth and progression." (PMID 24507701, 2014). "The prevalence rate of BRCA1 and BRCA2 mutations in this study is the lowest reported in South American studies with breast cancer populations unselected for age or family history." (PMID 24742220, 2014). "This study examines the frequency of BRCA1/2 defects among different breast cancer subtypes, and the ability of the HRD scores to identify breast tumors with defects in the homologous recombination DNA repair pathway." (PMID 25475740, 2014). "This role of VRK1 in DNA-damage response is in agreement with the predictive role of 53BP1 and BRCA1 expression in breast cancer." (PMID 24731990, 2014). "Here we report that two non-calcemic analogues of 1α,25-dihydroxyvitamin D3, seocalcitol (EB1089) and QW-1624F2-2, collaborate with BRCA1 in mediating growth inhibition of breast cancer cells and breast cancer stem-like cells." (PMID 25460500, 2014). "In English Springer Spaniels with mammary tumors, BRCA1 and BRCA2 genes seem to be involved in the development of the tumor." (PMID 24641873, 2014). "The 70 familial non-BRCA1/2 cases included in the current study, originated from 58 breast cancer families with tumor material from one affected family member and from 11 families with tumor material from more than one affected individual." (PMID 24479546, 2014). "BRCA1 and BRCA2 are the two major susceptibility genes involved in hereditary predisposition to breast cancer." (PMID 24834114, 2014).
breast cancer (continued). "We functionally demonstrated the interactions between miR-342, ID4 and BRCA1 in a model provided by ER-negative MDA-MB-231 breast cancer cell line that presented high levels of ID4." (PMID 24475217, 2014). "Twenty-one percent of the triple-negative tumors showed significant levels of methylation of the BRCA1 promoter, compared with <2% in each of the other breast cancer subtypes." (PMID 25475740, 2014). "This indicates that WBC harboring BRCA1 promoter methylation exhibit similar epigenetic changes in both breast cancer patients and cancer-free females." (PMID 25403427, 2014). "The median (95% CI) Kaplan-Meier estimate of survival time to breast cancer was 46.0 (44.9-48.1) years in the whole BRCA1 population, 53.7 (52.0-60.7) for menopause stratum, and 35.5 (32.9-38.3) for the ovulating population (p > 0.0001, log-rank test)." (PMID 25274085, 2014). "Pair 1 includes mother (#2) and two daughters (#5, #6), all are BRCA1+ and affected with breast cancer at 53, 36 and 36 years old respectively; Pair 2 includes mother (#4) and daughter (#7), both are BRCA1+ and were affected with breast cancer at 35 years old." (PMID 24884718, 2014). "A Phase II trial with olaparib was conducted on patients with advanced BRCA1/2 mutant breast cancers and ovarian cancers." (PMID 24795863, 2014). "In breast cancer, the BRCA1 DNA damage response protein is modified by the small ubiquitin-like modifier (SUMO) in response to genotoxic stress, and several SUMO E3 ligases are required for the downstream DNA damage response." (PMID 24874471, 2014). "The trinucleotide-repeat-containing 9 (TNRC9) gene has been shown to downregulate BRCA1 expression which results in breast cancer aggressiveness." (PMID 25051360, 2014). "Point mutations and sequence variants in BRCA1 and BRCA2 genes were previously identified in this cohort of Sri Lankan breast cancer patients." (PMID 24906410, 2014). "FANCD2 (12th) interacts with the BRCA1 and BRCA2 genes in the DNA repair process to reduce the risk of breast cancer." (PMID 24564336, 2014). "In order to identify breast cancer patients and cancer-free females harboring methylated BRCA1 promoter in their WBC, we screened 155 patients and 143 cancer-free females using the methylation-specific PCR (MSP) assay." (PMID 25403427, 2014). "This indicates that WBC from cancer-free females with methylated BRCA1 has abnormal gene expression profile similar to that seen in WBC from breast cancer cases." (PMID 25403427, 2014). "In the first discovery cohort, we genotyped four potential functional SNPs (rs3734091, rs56334522, rs28360342, and rs2035990) in 562 non-BRCA1/2 breast cancer patients and 504 controls." (PMID 25360583, 2014). "On the other hand, 5 genes were differentially expressed with significant difference between the breast cancer patients and carriers, BRCA1 (p = 0.03), BIRC5 (p = 0.035), CCND2 (p0.034), ATM (p = 0.012) and IGF1R (p = 0.025)." (PMID 25403427, 2014). "Further analysis revealed pathway-specific genetic driver mutations in breast cancer subtypes, such as BRCA1/2 alterations and PIK3CA alterations in basal-like and luminal breast cancers, respectively." (PMID 24874471, 2014). "A recent study has shown that variations in the BRCA1 and BRCA2 genes are associated with CMT in ESSs and these genes are responsible for early onset of breast cancer in women." (PMID 25293656, 2014). "We performed mutation analysis of BRCA1 and BRCA2 on unselected patients with breast cancer from the region of Medellin, Colombia." (PMID 24742220, 2014). "Germline mutations in BRCA1 and BRCA2 only explain the breast cancer risk in approximately one fourth of these families, however, it is expected that additional BRCA1/2 mutations still remain undetected by the screening methods used today." (PMID 24479546, 2014).
breast cancer (continued). "Germline mutations in the BRCA1 and BRCA2 breast cancer susceptibility genes have been associated with up to 15% of TNBC, and TNBC accounts for 70% of breast tumors arising in BRCA1 mutation carriers and 16–23% of breast tumors in BRCA2 carriers." (PMID 24970653, 2014). "In our study, we have shown that 10 out of 15 (66.7%) breast cancer patients, with methylated BRCA1 in their WBC, displayed BRCA1 methylation in paired tumor DNA." (PMID 25403427, 2014). "Hereditary BRCA1 and BRCA2 mutations account for about 60% of inherited breast cancer and are the only known causes of hereditary breast cancer syndrome." (PMID 24711893, 2014). "By age 70, approximately 60–70% and 45–55% of BRCA1 and BRCA2 mutation carriers will develop breast cancer, respectively; 40% and 20% of BRCA1 and BRCA2 mutation carriers will develop ovarian cancer." (PMID 24586286, 2014). "It is demonstrated, however, that basal BRCA1-related breast cancers originate from lumenal progenitor cells." (PMID 24722541, 2014). "Although BRCA1 and BRCA2 account for a high percentage of hereditary cases, there are more than 25 susceptibility genes that differentially impact the risk for breast cancer." (PMID 24830819, 2014). "Studies from our laboratory show that decreasing BRCA1 expression in breast cancer cells using shRNA markedly diminishes the activation of ERK1/2 signaling after radiation." (PMID 25174607, 2014). "The possibility that persistent replication stress is a tumour-promoting force in BRCA1mut/+ mammary epithelial cells offers, a hypothetical, mechanism-based route to BRCA1 breast cancer prevention." (PMID 25400221, 2014). "Incidence of breast cancer for all BRCA1 carriers was 321 events per 23,649 person-years of follow-up (PYFY), i.e. 0.014 (95% confidence interval, CI 0.012 0.015)." (PMID 25274085, 2014). "The CCND1, CCNB1, and STAT1 genes neighboring BRCA1 have also been reported to have important roles in breast cancer recurrence." (PMID 24497942, 2014). "In Canada and other countries, women with significant family history of breast and/or ovarian cancer are eligible for genetic testing for mutations in either one of the two breast cancer susceptibility genes, BRCA1 and BRCA2 (BRCA1/2)." (PMID 24667084, 2014). "In the present study, the association between the occurrence of BRCA1/2 mutations and the TNBC status among breast cancer patients from Sardinia was investigated." (PMID 24944648, 2014). "This is reminiscent of Rpn11 and BRCC36 (for BRCA1 (for Breast Cancer 1)/BRCA2 (for Breast Cancer 2)-Containing Complex subunit 36) found in the 26S proteasome lid and BRCC36-containing complexes, respectively, that are also inactive in the stand-alone form." (PMID 25144743, 2014). "The tumor suppressor function of HOXA9 has been extensively investigated in breast cancer where it has been shown that HOXA9 directly regulates BRCA1 and a number of other genes involved in invasion, growth and metastasis." (PMID 24886209, 2014). "Such mutations and sequence variants of BRCA1 and BRCA2 genes were previously identified in a group of Sri Lankan breast cancer patients." (PMID 24906410, 2014). "While BRCA1+ is inherited at the beginning of fertilization of the BRCA1+ carriers, breast cancer will only develop in the reproductive age." (PMID 24884718, 2014). "Under such a model, the effects of common breast cancer susceptibility variants and of BRCA1 and BRCA2 mutations on breast cancer risk would be multiplicative, after taking into account tumor ER status." (PMID 25919761, 2014). "Among the breast cancer–affected BRCA1 carriers, we had data on at least one disease characteristic of interest for 4,619 (59%) of the 7,797 affected women." (PMID 25919761, 2014). "Conversely, the tumor suppressor gene BRCA1, which has an important role in breast cancer, was also differentially expressed in allergen-challenged T cells." (PMID 24571673, 2014).